NCF4 (neutrophil cytosolic factor 4)
Diseases named in the same sentence as NCF4 in open-access papers (continued):
Sharing a sentence is not in itself a finding about the gene and the disease.
B-cell NHL (2 papers, 2017 to 2024). "Moreover, NCF4 rs1883112 was found as an independent predictor against hematologic, infectious and cardiac toxicity for aggressive B-cell non-Hodgkin lymphoma patients." (PMID 28938556, 2017). "Interestingly, in a previous study including an identification (n = 337) and a validation cohort (n = 572) of patients with aggressive B-cell NHL treated with doxorubicin-based chemotherapy, only the rs1883112 SNP in the NCF4 gene out of 53 candidate SNPs in 29 genes was successfully validated." (PMID 38835350, 2024).
clear cell renal cell carcinoma (2 papers, 2021 to 2024). "In our study, NCF1, NCF2, and NCF4 showed a high expression in renal clear cell carcinoma." (PMID 34708124, 2021).
COVID-19 (2 papers, 2022 to 2024). A disease caused by infection with severe acute respiratory syndrome coronavirus 2. "NCF4 has been shown to be a risk gene associated with the progression of kidney injury in COVID-19 patients." (PMID 38882332, 2024).
liver disease (2 papers, 2019 to 2022). "We then determined the genotypes in each group for CYBA-rs4673, NCF4-rs1883112, NOX4-rs1836882, rs3017887, SOD2-rs4880, and GCLM-rs41303970, and evaluated the association between these variants and HBV-induced liver diseases." (PMID 31969899, 2019). "We can only conclude that Nox4-rs1836882, rs3017887, NCF4-rs1883112, SOD2-rs4880, and GCLM-rs41303970 have statistically significant interactive functions in the development of HBV-induced liver disease." (PMID 31969899, 2019).
psoriasis (2 papers, 2014 to 2023). An autoimmune condition characterized by red, well-delineated plaques with silvery scales that are usually on the extensor surfaces and scalp. "Namely, RHCG, TCN1, KLK6, and LCN2 were chosen for psoriasis and CCL17, NCF4, BATF3, and CLEC4G as ACD-specific genes." (PMID 25058585, 2014). "Mice with a mutation in Ncf1 leading to a functionally deficient NCF1, but not the mutation of NCF4, regulate MIP, indicating that the NOX2 complex regulates psoriasis and autoimmune arthritis differentially." (PMID 37507888, 2023).
silicosis (2 papers, 2022 to 2024). Silicosis is a respiratory disease caused by breathing in (inhaling) silica dust. "In the present study, lungs of rat model of silicosis showed increased phagocyte NADPH oxidase activity with upregulated five structural components NOX2 (CYBB), p22phox (CYBA), p47phox (NCF1), p67phox (NCF2) and p40phox (NCF4)." (PMID 34991559, 2022).
staphylococcus aureus infection (2 papers, 2021 to 2025). An infectious process in which the bacteria Staphylococcus aureus is present. "High expression of NCF4 was associated with adaptive immune response (BP category), immunological synapse (CC category), immunoglobulin binding (MF category), and Staphylococcus aureus infection (KEGG category)." (PMID 34708124, 2021).
amoebiasis (1 paper, 2013). "Further analysis shows that anakinra works by binding receptor IL1R, which may influence multiple pathways like osteoclast differentiation pathway and amoebiasis pathway, affecting CD genes NCF4 and FN1 respectively." (PMID 24564553, 2013).
ankylosing spondylitis (1 paper, 2017). An autoimmune chronic inflammatory disorder characterized by inflammation in the vertebral joints of the spine and sacroiliac joints. "Aside from SLE and inflammatory bowel disease, genetic variation in p40phox (NCF4) has also been implicated in atopic dermatitis and ankylosing spondylitis." (PMID 28351984, 2017).
asthma (1 paper, 2021). "The levels of most proteins (ITGAM, ITGB2, MMP12, NCF1, NCF2, NCF4, RAC2 and Vav1) were higher in the asthma condition (shown in red) than those in the control condition or after SCIT condition." (PMID 34618857, 2021).
autoimmune disease (1 paper, 2020). A disorder resulting from loss of function or tissue destruction of an organ or multiple organs, arising from humoral or cellular immune responses of the individual to their own tissue constituents. "Apart from NCF1, several single nucleotide polymorphisms (SNPs) in NCF2, NCF4, and CYBA genes were reported to be associated with autoimmune diseases." (PMID 33145364, 2020).
bladder cancer (1 paper, 2021). "Wound healing assays and transwell assays were conducted simultaneously after NCF4 knockdown to figure out the potential role of NCF4 in the migration and invasion capacity of bladder cancer cells." (PMID 34708124, 2021).
Bovine mastitis (1 paper, 2015). INFLAMMATION of the UDDER in cows. "In this study, splice variants and functional single-nucleotide polymorphism (SNP) of NCF4 were identified to determine the variability and association of the gene with susceptibility to bovine mastitis characterized by inflammation." (PMID 26600390, 2015).
coronary artery disease (1 paper, 2020). "Some researches demonstrated that NCF4 might be a potential diagnostic biomarker or a regulatory target for acute myocardial infraction (AMI) and coronary artery disease." (PMID 32746852, 2020).
ischemic stroke (1 paper, 2020). A stroke disorder caused by obstruction of blood flow to the brain, due to thrombotic (local blood clot formation) or embolic (due to a blood clot or other material traveling from another site) event. "In the present study, we investigated the immune related gene expression modules, in which the SLAMF1, IL7R and NCF4 may be novel therapeutic targets to promote functional and histological recovery after ischemic stroke." (PMID 32746852, 2020).
kidney cancer (1 paper, 2021). Primary or metastatic malignant neoplasm involving the kidney. "Overexpression of NCF4 led to activation of the NADPH oxidase 2 complex and ROS production (activation of NADPH oxidase subunit NCF4 induces ROS-mediated EMT signaling in kidney cancer cells)." (PMID 34708124, 2021). "The data of the colony formation assay also showed that exogenous hydrogen peroxide increased the proliferation, whereas silencing NCF4 inhibited the proliferation in kidney cancer cells." (PMID 34708124, 2021). "NCF4 knockdown decreases the level of ROS in kidney cancer cells." (PMID 34708124, 2021).
latent adult autoimmune diabetes (1 paper, 2023). "Xing and colleagues found an increase in NCF4 expression in the neutrophils of patients with latent adult autoimmune diabetes (LADA), which contributed to oxidative damage to pancreatic beta-cells." (PMID 36902173, 2023).
myeloma (1 paper, 2021). "Moreover, compared to normal bone marrow plasma cells, patients with MGUS, or a smoldering myeloma, NOX2 (encoded by CYBB) is the only catalytic subunit expressed in MM patients along with the p40phox (NCF4) and p22phox (CYBA) regulatory subunits." (PMID 34067602, 2021).
Obesity (1 paper, 2019). Accumulation of substantial excess body fat. "The trend toward lower NCF-4 expression in obese group may be explained as a protective negative feedback phenomenon exerted by existing exaggerated oxidative stress associated with obesity." (PMID 31068904, 2019).
perianal Crohn disease (1 paper, 2017). A Crohn disease involving a pathogenic inflammatory response in the anal region. "In genetic studies the NCF4 gene (p40phox) locus has been found to be associated with ileal and perianal Crohn’s disease, supporting a role for NADPH oxidase dysfunction in the intestinal inflammation of IBD." (PMID 29062317, 2017).
prostate carcinoma (1 paper, 2024). A carcinoma that arises from epithelial cells of the prostate gland. "We then explored the expression of NCF4 in cell types in 12 primary prostate cancer samples from the single-cell dataset GSE141445." (PMID 38663915, 2024).
type 2 diabetes (1 paper, 2020). "We further measured and compared the gene expression of CXCR1, SELL, ITGA4, ITGAM, NCF4, ARHGAP3, and CLDN15 in neutrophils from 5 type 2 diabetes patients within 1 year from diagnosis and 5 age- and sex-matched healthy control subjects." (PMID 33391182, 2020).
tumor (13 papers, 2017 to 2024). "Elevated expression level of FYN (p value = 0.000), LCP2 (p value = 0.002), PTPRC (p value = 0.011), WAS (p value = 0.005), ZAP70 (p values = 0.000) and NCF4 (p values = 0.047) were associated with tumor size." (PMID 34834481, 2021). "Therefore, NCF4 rs1883112 G allele is expected to reduce the tumor cytotoxicity of R-CHOP chemotherapy." (PMID 28938556, 2017). "We further compared differences in inflammasome activation and tumor development in co-housed WT, Ncf4–/–, and Asc–/– mice." (PMID 38886341, 2024). "Pairwise analysis revealed that NCF4 expression was significantly higher in normal tissues than in tumor tissues in the TCGA-PRAD cohort (p=0.0053) and CPGEA cohort (p<0.001)." (PMID 38663915, 2024). "Our study implicates NCF4 in determining the spatial positioning of inflammasome assembly and contributing to inflammasome-mediated anti-tumor responses." (PMID 38886341, 2024). "This NCF4-coordinated response is necessary to trigger inflammasome-mediated activation and increase the population of anti-tumor CD8+ T and NK cells, preventing colorectal tumorigenesis." (PMID 38886341, 2024). "In this study, using RNA-seq data of 576 HCC patients, a panel of seven genes (including LCP2, TYROBP, ZAP70, PTPRC, FYN, WAS and NCF4) has been identified which are independent predictors of delayed tumor recurrence and improved patient prognosis." (PMID 34834481, 2021). "And we further proved that especially NCF1 and NCF4 were significantly correlated with high tumor grade and clinic stage." (PMID 34708124, 2021). "In order to preliminarily evaluate the role in tumorigenesis, we analyzed the different expression levels for NCF1, NCF2, and NCF4 between tumor and adjacent normal tissues in all TCGA tumors." (PMID 34708124, 2021). "Recent research published in the Journal of Pathology showed that genetic depletion of any of the NOX2 subunits Cyba, Cybb, Ncf1, Ncf2 and Ncf4 reduced the formation of lung metastases following intravenous injection of murine tumor cells." (PMID 30270440, 2019). "Furthermore, the expression or activity of MDSCs-associated molecules (ARG1, CYBB, iNOS, IL-10, NCF4, and TGF-β2) were significantly decreased from GPR84−/− mice in both LLC and B16F0 tumor models." (PMID 37105980, 2023). "In a recent contribution to The Journal of Pathology, van der Weyden et al2 reported that mice deficient in any of the five NOX2 subunits Cyba, Cybb, Ncf1, Ncf2 or Ncf4 were markedly less prone to develop lung metastases following intravenous injection of several histiotypes of tumor cells." (PMID 30270440, 2019). "These cells are associated with the inflammatory response and are implicated in multiple negatively regulated pathways that can facilitate the invasion and metastasis of tumor cells; in THn, CD38, NCF4, CRTAM, etc. are highly expressed." (PMID 39452125, 2024). "Differential expression was observed between tumor and normal tissues for NCF1, NCF2, and NCF4 in KIRC data from TCGA." (PMID 34708124, 2021). "The up-regulated CEP55, IFI44, NCF4, and TCIRG1 with HR > 1 were regarded as oncogenes and were proved to be closely related to tumor progression by using comprehensive bioinformatics analysis." (PMID 33101364, 2020). "These genes are involved in diverse cellular processes, including immunity (NCF4), regulation of glucose (FGF21), and a potential tumor suppressor (MCC)." (PMID 32531199, 2020). "Consistently, NCF4 was highly expressed predominantly in monocytes or macrophages and to a lesser extent in non-immune and tumor cells in the microenvironment." (PMID 38663915, 2024). "In summary, our study identified TOP2A, NCF4, FMNL1 and DOK3 as potential effective neoantigens for KIRC mRNA vaccine development, and patients with RIS2 tumor might benefit more from mRNA vaccination." (PMID 34872567, 2021).
tumor (continued). "Finally, we isolated the CD15+ cells and CD4/CD8pos T cells at 24 h from APCCs and analyzed the expression of key immune‐suppressive genes of MDSCs (ARG1, NCF1, NCF4, CYBB) which mediate MDSC arginase 1 secretion and NO generation to inhibit T cells within the tumor TME." (PMID 35611994, 2022). "Interestingly, the expression of NCF4 and NCF1, but not that of NCF2, was significantly downregulated in tumor tissues compared to that in control tissues." (PMID 38886341, 2024).
infection (12 papers, 2008 to 2025). The state of being infected such as from the introduction of a foreign agent such as serum, vaccine, antigenic substance or organism. "Thus, downregulation of these transcripts and an increase of miR-3944-5p, accounting for the decrease seen in its target, NCF4 mRNA, could represent a mechanism of survival elicited by infection." (PMID 39028711, 2024). "Eight genes (NCF4, CD14, IL17D, CD1D, CD163, IL1R2, TLR9, and TLR2) with different expression in each infection group were selected for qPCR analysis." (PMID 25906258, 2015). "NCF4 (OMIM 601488) which transcribes a subunit (p40-phox) of NAPDH oxidase which activates the NLRP3 inflammasome, and NLRP3 (OMIM 606416) were both induced by PBA during infection, at 24 and 72 hrs, respectively (P≤0.026)." (PMID 26133770, 2015). "Furthermore, within the transcription factor-gene network, SPI1 is closely related to NCF4 and CEBPA, both of which have a role in macrophage activation and infection response." (PMID 40677917, 2025). "Notably, the levels of activated caspase-1 and released IL-1β in response to LPS and ATP, which activate the NLRP3 inflammasome; dsDNA transfection and infection with F. novicida, both as activators of the AIM2 inflammasome, were reduced following transfection with Ncf1, Ncf2, or Ncf4 siRNAs." (PMID 38886341, 2024). "However, mutating Ncf4 and Nox4, two murine orthologs (pentagons) of the non-disease proteins (but PC members) NCF4 and NOX4, causes the phenotype Increased susceptibility to infection in mouse." (PMID 32591566, 2020).
cancer (5 papers, 2021 to 2025). A tumor composed of atypical neoplastic, often pleomorphic cells that invade other tissues. "In a study of 97 consecutive decedents with a cancer diagnosis (48 of whom were treated with anthracyclines), cardiac histological lesions and NCF4 rs1883112 were shown to be highly linked with cardiac fibrosis." (PMID 40362292, 2025). "We observed more frequent high-grade dysplasia, increased severity of the damage, and malignant tumors in Ncf4–/– mice than in WT mice." (PMID 38886341, 2024).
adenocarcinoma (1 paper, 2015). A common cancer characterized by the presence of malignant glandular cells. "TGF-β can also induce NOX2 gene expression and its activation dependent on p40phox subunit (NCF4) in adenocarcinoma Hela cells." (PMID 26078812, 2015).
cardiovascular diseases (1 paper, 2020). "We suspect that NCF4 act on similar modes and approaches in cerebral vascular diseases compared to those of the cardiovascular diseases." (PMID 32746852, 2020).
NCF4 also shares sentences with these, for which no sentence is quoted: Autoimmunity (4 papers); immune disorder (4); Immunodeficiency (3); bacterial infection (2); diffuse large B-cell lymphoma (2); multiple sclerosis (2); Sepsis (2); acute lymphoblastic leukemia (1); Alzheimer disease (1); aspergillosis (1); atherosclerosis (1); atopic dermatitis (1); autosomal recessive HIES (1); breast carcinoma (1); cardiac hypertrophy (1); Cerebral ischemia (1); chronic hepatitis B (1); cognitive decline (1); Cognitive impairment (1); colon cancer (1); Comèl Netherton syndrome (1); diabetes (1); endometriosis (1); enterocolitis (1); glioblastoma (1); hepatocellular carcinoma (1); Hyperglycemia (1); hypogammaglobulinemia (1); infectious colitis (1); infectious disease (1).
A further 22 diseases each share a sentence with NCF4 in 1 paper.